NPC1 (NPC intracellular cholesterol transporter 1)
Diseases named in the same sentence as NPC1 in open-access papers (continued):
Sharing a sentence is not in itself a finding about the gene and the disease.
infection (81 papers, 2012 to 2026). The state of being infected such as from the introduction of a foreign agent such as serum, vaccine, antigenic substance or organism. "Although mutagenesis had occurred in only one of the two alleles, these cells, named NPC1 KD, showed significantly greater resistance to infection when challenged with VSV-Spike-GFP under conditions comparable to those used for U18666A-treated cells." (PMID 39707537, 2024). "The Tubeimosides’ antiviral activity and NPC1 function are further confirmed by infection with SARS-CoV-2 variants of concern (VOC), SARS-CoV, and MERS-CoV." (PMID 38167417, 2024). "In this context, analysis of Pearson correlation coefficients revealed a significant linear correlation between NPC1-expressing cells and Spike-positive cells, confirming the strong association between NPC1 expression and infection ratios." (PMID 39707537, 2024). "Limiting the spread of viruses in bats and increasing human susceptibility to infections have both been linked to genetic changes in the NPC1 gene, which encodes the endo-lysosomal NPC1." (PMID 38098077, 2023). "NPC1 is a lysosomal MP essential for cellular cholesterol homeostasis and susceptibility to infections caused by Ebola, other filoviruses, hepatitis virus, flaviviruses, SARS-CoV-2, SARS-CoV-1, and F-CoV." (PMID 38098077, 2023). "A site-directed mutagenesis study further demonstrated that cells expressing NPC1 with E426 were susceptible to EBOV GP-mediated infection, while exhibiting lower susceptibility to MARV GP-mediated infection." (PMID 34069246, 2021). "The A82V mutation promotes the conformational changes induced by Niemann–Pick C1 (NPC1) binding, and the T544I mutation mediates membrane fusion and infection." (PMID 29300152, 2018). "In this study, we show that interactions between filoviruses and their entry receptor NPC1 can influence the cellular susceptibility of bats to infection." (PMID 26698106, 2015). "We have identified an NPC2 deficient cell line (NPCD55) that loses expression of NPC1 upon infection by HIV-1." (PMID 22273177, 2012). "NPC1-deficient cells are unable to support the delivery of transcriptionally active reovirus core particles to the host cytoplasm, whereas treatment with hydroxypropyl-β-cyclodextrin, which binds and solubilizes cholesterol, restores infection." (PMID 35320319, 2022). "Thus, reovirus cannot launch infection from endocytic vesicles that are disrupted by the loss of WDR81 or NPC1." (PMID 35320319, 2022). "The endosomal entry of EBOV is by GP1, while the low pH membrane fusion is coordinated by GP2 using Neimann-Pick C1 protein (NPC1), and thus implicated as major pathogenic determinants for infection and the main target for the development of a vaccine for Ebola virus." (PMID 31569539, 2019). "This is the second human pathogen whose mechanism of infection has been linked to host NPC1." (PMID 28008422, 2016). "Therefore, strong reductions in the affinity of virus-NPC1 recognition are predicted to reduce or eliminate infection in whole bat hosts, as observed in NPC1-deficient mice, barring viral mutation to enhance this affinity." (PMID 26698106, 2015). "Such inner viral membrane proteins might be implicated in the cell—virus fusion step during infection, and the target receptors in the host cell are cellular endosomal proteins, such as Niemann-Pick C type 1 (NPC1) and lysosomal membrane proteins (Lamp−1 and −2)." (PMID 37711186, 2023). "Currently, we are unable to fully explain the differences between these data, but one possibility is that infection with live mycobacteria achieves greater inhibition of NPC1 activity, and as a consequence protein abundance is increased in an attempt to compensate for the loss of NPC1 function." (PMID 36085278, 2022). "This study represents the first report linking NPC1 to the infection process of a plant virus, expanding our understanding of plant-virus interactions." (PMID 42198778, 2026).
infection (continued). "NPC1 is a transmembrane protein involved in cholesterol transport in animal cells, but also in the infection by several viruses of different families." (PMID 42198778, 2026). "Analysis of available RNAseq (INRP000146) data for uninfected, LD-S and LD-R-infected-PEC revealed a suppression of Npc1 expression along with its transcription factor Srebp2, in response to LD-R-infection." (PMID 40424189, 2025). "To test if the reduction in SARS-CoV-2 infectivity was due specifically to an effect on the early steps of viral infectious cycle, we performed a synchronized infection of Caco-2 WT and NPC1 KD cells by incubating the cells with the virus on ice for 1 h." (PMID 39707537, 2024). "Subsequent epitope mapping and sequence alignment revealed that the main epitopes of TPO and NPC1, which display elevated autoantibody levels after infection, have a sequence similarity containing five identical residues." (PMID 39414823, 2024). "NPC1 inactivation was accomplished either by using the drug U18666A or by CRISPR/R-Cas9 NPC1 gene editing, and cell infection was carried out using a pseudotyped vesicular stomatitis virus (VSV) expressing the SARS-CoV-2 S protein." (PMID 39707537, 2024). "Further linking endolysosomal acidification with viral entry and NPC1, an increase in the acidic pH in this location also impaired S1 function, thereby protecting cells from infection." (PMID 39408818, 2024). "Lastly, we also provided a more concrete demonstration that the deficit of NPC1 function has a protective effect against VSV-Spike-GFP infection by infecting increasing amounts of NPC1 KD cells mixed with a fixed amount of WT cells." (PMID 39707537, 2024). "SARS1-S and MERS-S pseudoviruses productively infected Caco2 WT cells and Vero WT-A-T cells, and NPC1-KO strongly reduced these infections." (PMID 38167417, 2024). "Vice versa, pharmacological inhibition of NPC1 strongly reduces infection with SARS-CoV-2 and interferes with the fusion of viral envelopes with late endosomal membranes." (PMID 39408818, 2024). "The NPC1-mediated intracellular cholesterol transport pathway is essential for the successful infection of HIV-1 and HAV." (PMID 37710249, 2023). "Knockout cells for CCZ1, NPC1 or RAB7 genes survived the VSVΔG/MARVGP infection and expanded over time, in contrast to GFP-expressing WT cells, confirming the role of these genes in VSVΔG/MARVGP infections." (PMID 37880247, 2023). "A cell’s susceptibility to infection by filoviruses like the Ebola virus (EBOV) and Marburg depends, in large part, on NPC1." (PMID 38098077, 2023). "beforetoHIV-1 and HAV both rely on the NPC1-mediated intracellular cholesterol transport pathway for successful infection." (PMID 37710249, 2023). "Knocking-out CCZ1 and RAB7 resulted in more than 98% decrease in the relative level of infection, whereas we observed residual infection in NPC1 mutant A549 cells." (PMID 37880247, 2023). "NPC1 is a crucial viral receptor and an essential host component for filovirus entrance, infection, and pathogenesis." (PMID 38098077, 2023). "As expected, the knockout of rab7 and npc1 lead to a dramatic decrease in infection (98.4% and 99.99% respectively), mainly recovered in inverted cells." (PMID 37880247, 2023). "Our previous study suggested that Niemann-Pick C1 (NPC1) is an essential host factor for baculovirus entry and infection in cells of the B. mori cell line BmE." (PMID 35867410, 2022). "In our previous study, we demonstrated that baculovirus entry and infection in BmE cells rely on the host factor NPC1 and that gp64 can interact with NPC1 directly." (PMID 35867410, 2022). "Although the estimated accuracy of our NPC1 model was low across mammals overall, the final model successfully predicted infection status of bat species included in the model with high accuracy." (PMID 36542657, 2022).
infection (continued). "The disruption of this interaction by drugs that are known to interact with NPC1, causes a reduction in the viral replication, and it is currently accepted that NPC1 is pivotal for a successful infection in several virus models." (PMID 35081156, 2022). "Colocalization between viral cores and Rab7 (labelled LE) increased in NPC1 KO cells early after infection." (PMID 35081156, 2022). "Niemann Pick C1 (NPC1) receptor sequences predicted infection statuses of bats included in our study with very high accuracy, suggesting that characterizing NPC1 in additional species is a promising avenue for future work." (PMID 36542657, 2022). "It has been demonstrated the importance of both NPC1 and cholesterol transport for a successful infection of a variety of viruses." (PMID 35081156, 2022). "The endo-lysosomal host–pathogen interface involving NPC1 is a critical host factor in the infection cycle of many viruses." (PMID 35631123, 2022). "In our NPC1 model, residues that confer high affinity to binding with wild type filovirus glycoproteins strongly determined infection status." (PMID 36542657, 2022). "NPC1 has also been identified as a filovirus receptor fusing to the glycoproteins of filovirus envelopes and facilitating cell infection." (PMID 36542657, 2022). "Our results indicated that antiviral drugs targeting NPC1-viral protein interaction are able to decrease infection." (PMID 35081156, 2022). "Even models of NPC1 with nuisance variables of sampling effort and distance to spillover site still found significant positive infection in species with residue A at position 425 and marginal significance for other residues in positions 425–427." (PMID 36542657, 2022). "Cells defective for the homotypic fusion and protein sorting (HOPS) complex or NPC1 function, including primary fibroblasts derived from human NPC1 disease patients, are resistant to infection by Ebola and Marburg viruses." (PMID 34248884, 2021). "Transcripts similar to p-Obps showed a greater reduction only on day 2 while Niemann-Pick C1 (NPC1), showed a considerable reduction after day 2 of infection." (PMID 34988032, 2021). "Studies using an NPC1-specific short interfering RNA (siRNA) and a cell line with dysfunctional NPC1 demonstrated that NPC1 function is required for cholesterol acquisition by A. phagocytophilum and infection." (PMID 34544283, 2021). "Engagement of GPCL with the universal filoviral intracellular receptor Niemann-Pick C1 (NPC1) eventually culminates in fusion between viral and cellular membranes, cytoplasmic escape of the viral nucleocapsid, and subsequent infection." (PMID 33436438, 2021). "This was most notable for toremifene, clomifene, and sertraline, suggesting that they (in addition) also acted via the GPCL-NPC1 axis; overexpression of NPC1 clearly counteracted their inhibitory mechanism during infection." (PMID 33436438, 2021). "Interaction of the filovirus spike protein GP with its universal intracellular receptor NPC1 is indispensable for viral entry and infection (9, –, 13)." (PMID 33436438, 2021). "According to NPC1 expression, low, moderate and high cell cultures were able to be delineated, which upon infection with EBOV seemed to reveal a potential correlation between NPC1 expression levels and virus titers." (PMID 31961874, 2020). "We previously reported that U18666A inhibits cholesterol transport and type I FIPV infection by acting on a cholesterol transporter, Niemann-Pick C1 protein (NPC1)." (PMID 30658691, 2019). "A similar scenario has been observed in resistant lymphocytic cell lines, which clearly express NPC1 yet they are resistant to infection." (PMID 30893855, 2019). "In line with the notion that enhanced LE/L cholesterol negatively affects IAV early infection, the proportion of infected cells strongly increased (62.0% ± 4.62%) when NPC1 was transiently coexpressed together with AnxA6 in these cells." (PMID 30042202, 2018).
infection (continued). "Additional insight into the molecular mechanism of the virus GP-NPC1 interaction and infection pathogenesis is required to fully understand the role of NPC1 in EBOV infection." (PMID 28913343, 2017). "Within 24 h of infection, A. phagocytophilum recruited NPC1 to the inclusion membrane via NPC1-positive, LAMP1/2-negative vesicles." (PMID 28529926, 2017). "Whereas human cells can be infected by EBOV, a cell line derived from a Russell’s viper (Daboia russellii) (VH-2) is resistant to infection in an NPC1-dependent manner." (PMID 27303731, 2016). "Transgene and control viral vectors were injected into the deep cerebellar nuclei of Npc1 flox/-;Pcp2-Cre mice at 6 weeks and animals were examined four weeks post-infection." (PMID 27152617, 2016). "This resistance to infection can be mapped to a single amino acid residue in viper NPC1 that renders it unable to bind to EBOV GP." (PMID 27303731, 2016). "Two immune-related genes, a Niemann Pick-type C1 (NPC1) gene (AAEL009531) and Toll1A (AAEL007613), are also found in the region associated with resistance and were upregulated in response to infection in one or both genotypes." (PMID 25815506, 2015). "Moreover, NPC1 is an essential antigen receptor and an important component of filovirus entry into the host to initiate infection and pathogenesis." (PMID 41011350, 2025). "Indeed, the infection of NPC1 KD cells with pseudotyped VSV-Spike-GFP virus resulted in ~ 3% GFP-positive cells compared to ~ 60% GFP-positive cells in WT Caco-2 cells." (PMID 39707537, 2024). "Overall, based on the key role of LDL endocytic routes, here we explored the participation of NPC1 in B. besnoiti tachyzoite proliferation, thereby presenting the first report on this sterol carrier for B. besnoiti infections in primary bovine endothelial cells." (PMID 39183751, 2024). "Furthermore, the reduction of ACE2 at the PM and its targeting to the autophagolysosomal compartment in NPC1 KD cells indicate that the molecular basis of infection resistance in NPC1 KD cells and U18666A-treated cells is similar." (PMID 39707537, 2024). "Next, NPC1-KO cell lines were used for infection with these pseudoviruses." (PMID 38167417, 2024). "Recent research has uncovered NPC1’s function within the infection process of several viruses." (PMID 38098077, 2023). "That our NPC1 models predicted the infection status of bats from multiple families with high accuracy suggests that available bat trait and phylogenetic data do not adequately capture cross-species differences in immune functioning that can explain infection status." (PMID 36542657, 2022). "Patients with NPC1 suffer from a severe life-limiting disease, the potential risks of TNF therapy (demyelination and increased infection susceptibility) must be balanced against the improvement in quality of life due to effective IBD therapy and symptom control." (PMID 35694196, 2022). "We found NPC1 sequences predicted infection status in bats with high accuracy and that key amino acid positions thought to confer resistance to filoviruses were significant predictors of infection status." (PMID 36542657, 2022). "Alternatively, infection by VSV-EBO GP (GFP) is blocked at a step following NPC1 interaction." (PMID 35320319, 2022). "The NPC-1 is a multi-functional gene which not only serves as an intercellular cholesterol transport protein, but also as a cytomembrane receptor to mediate cell infection by a wide range of viruses." (PMID 35621772, 2022). "To determine whether NPC1 KO affects total virus yield, we checked viral titers in supernatants at 24 h post-infection with BTV-8." (PMID 35631123, 2022). "For this purpose, BmE cells and NPC1-null cells were inoculated with virus VP39 labeled with enhanced green fluorescent protein (VP39-EGFP) at a multiplicity of infection (MOI) of 80 at 4°C for 1h, then shifted to 28°C for 2 h post-virus inoculation before being imaged by confocal microscopy." (PMID 35867410, 2022).
infection (continued). "We also model infection status as a function of NPC1 amino acid sequence data." (PMID 36542657, 2022). "Editing of these genes, including those encoding CTSL, cholesterol transporters NPC1/2, WDR81/91, and TFE3, markedly reduced infection, suggesting that Sdel and SARS-CoV may utilize similar entry machinery in this cell type." (PMID 33574281, 2021). "Interestingly, EBOV infection was not increased following NPC1 upregulation, indicating a changing importance of NPC1 during the course of infection." (PMID 34834992, 2021). "Importantly, as both ebolaviruses and marburgviruses require GPcl binding to NPC1 to facilitate infection, the pocket serves as a target for panfilovirus inhibitors." (PMID 34069246, 2021). "These are promising results for further in vitro infection experiments in M. condylurus cells, to prove whether NPC1 expression levels correlate with the replication of infectious EBOV particles in primary cells." (PMID 31961874, 2020). "Previous work in this lab has demonstrated incompatibilities in the NPC1 filovirus receptor which render PaKiT01 cells refractory to infection with rVSV-MARV (Ng and Chandrab, 2018, Unpublished results), making them structurally antiviral, over and above their constitutive expression of IFN-α." (PMID 32011232, 2020). "We hypothesize that low NPC1 expression would facilitate viral persistence in the host by imparting a divergent tissue tropism, one that leads to asymptomatic infection profiles." (PMID 31961874, 2020). "How the suspected temperature adaptations are influencing the NPC1 expression levels and how high ambient temperatures might influence the course of infection with EBOV needs to be addressed in further investigations." (PMID 31961874, 2020). "In addition, in viruses other than type I FCoV, ICZ inhibits infection by acting on proteins other than NPC1." (PMID 30658691, 2019). "We speculate that NPC1 is the common entry host factor for many enveloped viruses during cellular infection." (PMID 31866985, 2019). "Besides, the expressions of Nieman-Pick C1 (NPC1), integrin αV, and Mer have been reported to be essential for the infection of macrophages by EBOV GP." (PMID 31569539, 2019). "To investigate whether BmNPC1 is involved in BmNPV infection in insect cells, we first examined the effect of two small molecule NPC1 antagonists on BmNPV-EGFP infection in BmE cells." (PMID 31866985, 2019). "In summary, in NPC1-inhibited A549 cells, through either AnxA6 expression or U18666A treatment, the cholesterol imbalance in the LE/L compartment restricted the first infection cycle of incoming IAV particles, independently of the antiviral properties of IFITM3." (PMID 30042202, 2018). "Hence apilimod appears to block filoviral entry and infection by inhibiting virus particle trafficking to NPC1+ endolysosomes, the portal for entry of the EBOV genome into the host cell cytoplasm." (PMID 28403145, 2017). "We demonstrate that cells derived from the Russell’s viper are not susceptible to infection because EBOV cannot bind to viper NPC1." (PMID 27303731, 2016). "However, the enhanced copy number of NPC1 protein will still be subject to inhibition by mycobacterial lipids, so cannot prevent the development of stable infection over time." (PMID 28008422, 2016). "We and others recently demonstrated that Niemann-Pick C1 (NPC1), a large endo/lysosomal membrane protein involved in cellular cholesterol trafficking, is an essential intracellular receptor for filovirus entry and infection (20, –, 23)." (PMID 27303731, 2016). "No detectable infection was obtained with either virus in NPC1-deficient cells, indicating that filovirus entry into these cells is absolutely dependent on the E. helvum NPC1 ortholog." (PMID 26698106, 2015).